MMP1 (matrix metallopeptidase 1)
Diseases named in the same sentence as MMP1 in open-access papers (continued):
Sharing a sentence is not in itself a finding about the gene and the disease.
pulmonary fibrosis (continued). "In addition to aging, MMP1 is a biomarker for several cancers, pulmonary fibrosis and potentially Alzheimer’s disease, whereas STC1 is a diagnostic and prognostic biomarker for cancers, pulmonary fibrosis, renal ischemia/reperfusion injury and Alzheimer’s disease." (PMID 33210602, 2020). "The metalloproteinases MMP-1 (Matrix Metalloproteinase-1) and MMP-7 (Matrix Metalloproteinase-7) are defined as potential peripheral blood biomarkers in idiopathic pulmonary fibrosis (IPF)." (PMID 40733571, 2025). "Rapamycin alleviates alveolitis and pulmonary fibrosis in the BLM-induced pulmonary fibrosis rat model by reducing the production of matrix metalloproteinase (MMP)-9 and tissue inhibitors of MMP-1 in lung tissue." (PMID 40665395, 2025). "The exact role of MMP-1, as well as the inhibition effect of MR on MMP-1 activity in pulmonary fibrosis need further investigation." (PMID 38895626, 2024). "For instance, one study integrated conductive MIMs with extended gate FET (EG-FET) sensors to identify specific antigenic regions of matrix metalloproteinase-1 (MMP-1) protein, a biomarker of idiopathic pulmonary fibrosis (IPF)." (PMID 39204816, 2024). "Proinflammatory cytokines in SARS-CoV-2 infection are also believed to increase matrix metallopeptidase 1 (MMP1) and MMP7 expression, which degrades the ECM and contributes to airway remodeling and pulmonary fibrosis." (PMID 37893011, 2023). "MMP1 is a multifunctional protease responsible for degrading components of the extracellular matrix (ECM) and plays a key role in pulmonary fibrosis." (PMID 37221600, 2023). "In pulmonary fibrosis, fibrosis-related factors such as chemokines (IL-8, CCL18), proteases (MMP-1, MMP-7) or growth factors have been suggested to have diagnostic potential for fibrosis, but their utility in clinical routine has not been established." (PMID 37814303, 2023). "MMP1 is well represented in neoplasms, promoting the spreading of metastases and their invasive potential, and enhancing the EMT in pulmonary fibrosis, angiogenesis and cell migration." (PMID 36553114, 2022). "Previous studies showed that particularly MMP-1, -2, -3, -9 and -13 were upregulated in IPF patients and experimental models of lung fibrosis." (PMID 35804363, 2022). "For example, matrix metalloproteinase-1 (MMP-1), the key enzyme responsible for collagen digestion, was found to be significantly decreased and its inhibitor increased in a rat model of pulmonary fibrosis." (PMID 33250776, 2020). "Because mice lack the orthologue of human MMP-1 and in view of our clinical data, we further investigated the role of MMP-13 in the murine model of bleomycin-induced lung fibrosis." (PMID 24023851, 2013). "Previous reports provided evidence about the role of MMP-1 and MMP-8, also known as collagenase 1 and collagenase 2, respectively, in the development of idiopathic pulmonary fibrosis, ischemic stroke, small vessel stroke, acute hepatitis, and various cancer types." (PMID 36860404, 2023). "Additionally, matrix metalloproteinase 1 (MMP1) and matrix metalloproteinase 7 (MMP7) are found in the peripheral blood of individuals with IPF and are highly overexpressed in lung fibrosis and reflect disease progression." (PMID 36056418, 2022). "This could imply that the elevations in circulating MMP1 and MMP2 expression we observed in patients with IPF are a failed attempt to control lung fibrosis." (PMID 32171287, 2020). "However, our group found an increase in serum biomarkers of pulmonary fibrosis (MMP7, MMP1, and periostin) in patients with early fibrotic changes in chest CT at 2 months after hospital discharge, not only in IMV patients but also in those treated with conventional or high flow nasal cannula oxygen." (PMID 36096801, 2022).
pulmonary fibrosis (continued). "Additional collagenases may exert a major role in lung homeostasis, possibly MMP-8 and MMP-13, which are also found to be induced in chronic obstructive pulmonary disease, or MMP-1, which is absent in fibroblast foci from idiopathic pulmonary fibrosis." (PMID 27066886, 2016).
skin aging (50 papers, 2009 to 2025). The gradual irreversible changes in structure of skin that occur as a result of the passage of time.. "ROS upregulate various signaling pathways, such as MAPKs, AP-1, and NF-κB, which are associated with MMP-1 production and proinflammatory cytokines, contributing to skin aging." (PMID 37891882, 2023). "It is a well-known fact that UVA radiation-induced premature skin aging was associated with MMP-1 activation and collagen degradation events." (PMID 32104530, 2020). "We propose that skullcapflavone II would be a useful chemopreventive compound for treating physiological conditions associated with up-regulation of MMP-1 and the loss of extracellular matrix integrity, such as skin aging." (PMID 31167359, 2019). "Previous studies have reported that MMP-1 expression is closely associated with skin aging." (PMID 40374763, 2025). "Recently, it was reported that hydrogen may suppress the formation of ROS caused by UV and the expression of MMP-1, thus preventing the UV-exposed skin aging." (PMID 33419292, 2020). "The increase in MMP1 after ultraviolet irradiation of the skin suggests a degradation of these collagen fibers, a loss of mechanical firmness of the skin and the ability to stretch the skin, as well as a decrease in skin elasticity, and all these cause the appearance of signs of skin aging." (PMID 37299236, 2023). "Matrix metalloproteinases (MMPs), particularly MMP-1 and MMP-9, play a key role in extracellular matrix (ECM) degradation and are closely associated with the progression of skin aging." (PMID 41375950, 2025). "Before evaluating the protective effects of genistein against PM-induced skin aging, we assessed its cytotoxicity and effects on MMP-1 expression in HaCaT cells." (PMID 41304992, 2025). "M-Gly also upregulated type I procollagen expression and reduced MMP-1 level in photoaged skin, demonstrating a protective effect during the process of UV-induced skin aging." (PMID 39857364, 2024). "In skin aging models, MMP-1 and MMP-2 levels were reduced after application of all tested substances." (PMID 36838716, 2023). "The activation of MMP-1 and the degradation of type I collagen are two main markers related to skin aging." (PMID 37149635, 2023). "HYP is an important component of fibrillar collagen and MMP-1 degrades collagen fibers in extracellular matrix, both of which are closely related to skin aging." (PMID 36618934, 2022). "We then found increases in mRNA and protein levels, along with activity of matrix metalloprotease (MMP)-1 and MMP-3, which are associated with skin aging following DPE exposure." (PMID 35269833, 2022). "We measured the type I procollagen and MMP1 level that are the main factors related to skin aging in HDFs." (PMID 33513930, 2021). "UV irradiation increases the expression of matrix metalloproteinase-1 (MMP-1), a collagen-degrading enzyme, and promotes collagen degradation, which contributes to skin aging." (PMID 35054431, 2021). "As degradation of collagen is known to be the primary reason for UV-mediated skin aging, blocking MMP-1 activity or expression has been recognized as a promising strategy for preventing skin aging." (PMID 33322005, 2020). "In order to examine the preventive potential of propolis against skin aging, we examined the effect of propolis on UV-induced MMP-1 levels in Hs68 human dermal fibroblasts (HDFs)." (PMID 33322005, 2020). "Taken together, these results provide evidence that caviar extract acts as an adiponectin inducer that inhibits UVB-irradiation-induced skin aging by suppressing MMP-1 gene expression." (PMID 32403430, 2020). "The accumulation of ROS has been reported to induce skin aging through the expression of MMPs, including MMP-1, MMP-2, and MMP-9." (PMID 30669248, 2019). "Among the UV-inducible enzymes, MMP-1 has been known to play a key role in collagen degradation, and thus has been a major interest in skin aging." (PMID 31234539, 2019).
skin aging (continued). "The dose-dependent inhibition of MMP-1 expression and promotion of type-1 procollagen expression by the treatment with SMGGT demonstrates the clinical efficacy of this preparation for skin aging caused by extrinsic stresses including sunlight." (PMID 27052448, 2016). "UVB-induced skin aging is primarily caused by the activation of the MAPK pathways (ERK, JNK, and p38) and AP-1 transcription factors (c-Fos/c-Jun), which upregulate MMP-1 and other matrix metalloproteinases that degrade collagen in the dermal extracellular matrix." (PMID 40864771, 2025). "Furthermore, we indicated that MMP1 activities markedly downregulated after EGCG against UVR induced-skin aging." (PMID 38304421, 2024). "Luteolin may be potentially useful in the prevention of skin aging by inhibiting the UVA-induced production of collagen MMP-1." (PMID 32802136, 2020). "Therefore, MMP-1 inhibitors can be an attractive strategy in preventing skin aging due to UV exposure." (PMID 31234539, 2019). "In addition, PM-induced oxidative stress promoted via the production of ROS and subsequent increase in the activity of matrix metalloproteinases (MMPs), including MMP-1, MMP-2, and MMP-9, can cause skin aging as a consequence of the degradation of collagen." (PMID 30669248, 2019). "Therefore, the expression of COL‐1, COL‐3, ELN, and MMP‐1 is closely related to skin aging." (PMID 40012471, 2025). "Therefore, the inhibition of MMP-1 and increased type 1 collagen prevents skin aging." (PMID 37891882, 2023). "Furthermore, our results demonstrate a novel role for AA in preventing UV-induced MMP-1 expression, suggesting that p300 inhibitors such as AA could be used for anti-skin aging cosmetics or drugs." (PMID 19287485, 2009). "Their findings revealed that these masks repressed matrix metalloproteinase-1 (MMP-1) and increased collagen type I, thereby reducing skin aging." (PMID 40863616, 2025). "We focused on MMP-1, COX-2, and IL-6 to elucidate the molecular mechanisms by which luteolin mitigates PM-induced skin aging and inflammation." (PMID 40374763, 2025). "These compounds were shown to reduce oxidative stress, inhibit MMP-1 secretion, promote COLIA1 expression, and suppress ERK phosphorylation, highlighting their potential as multifunctional agents for combating skin aging." (PMID 41375950, 2025). "First, harringtonine markedly suppressed the expression of matrix metalloproteinases (MMP-1, MMP-2, and MMP-9), which are critical mediators of ECM degradation and play central roles in the pathogenesis of skin aging and photoaging." (PMID 40864795, 2025). "In order to develop effective natural materials that can prevent skin aging, new materials were sought through in vitro evaluation focusing on AQP3, HAS3, and MMP-1 mechanisms." (PMID 36250021, 2022). "Next we investigated levels of MMP-1 and MMP-3, which are involved in skin aging development by alteration of the extracellular matrix structure, in HDF." (PMID 35269833, 2022). "The results suggested that LNF is non-toxic to dermal fibroblast cells and can inhibit the secretion of MMP1, MMP9, IL-6 and IL-8 upon UV-induced skin aging." (PMID 35215366, 2022). "Collagenase, particularly MMP-1 (collagenase-1), is the MMP that is most strongly influenced by UV stimulation and is directly related to skin aging." (PMID 34122721, 2021). "MMP-1 can degrade these two kinds of collagen fibers and reconstitute the ECM, resulting in wrinkles, sagging, and other signs of skin aging." (PMID 32627834, 2020). "As PI3K can promote the expression of MMP-1 leading to collagen breakdown, targeting PI3K can provide a therapeutic window to effectively regulate MMP-1 levels and prevent skin aging." (PMID 33322005, 2020).
skin aging (continued). "At the same time, SIP decreased the ROS induced up-regulation of MMP1 and MMP9 to ease MMP-mediated skin aging." (PMID 32009967, 2019). "Taken together, our findings provide evidence that quercetin attenuates UV-stimulated MMP-1 and COX-2 expressions via direct inhibition of JAK2 and PKCδ kinase activities, thereby preventing UV-induced skin aging." (PMID 31652815, 2019). "Concurrently, squid ink polysaccharides decrease the ROS induced up-regulation of MMP1 and MMP9 to decrease MMP-mediated skin aging." (PMID 32009967, 2019). "MMP-1 and MMP-9 play an important role in type I collagen synthesis, inhibition of its expression is a way to prevent or mitigate UV-induced skin aging, and secretion of type I procollagen is important to provide structural support of skin." (PMID 31762729, 2019). "In conclusion, NR, R, and particularly RR have been shown to control MMP-1-mediated UVB-induced skin aging, apoptosis-induced skin aging, and inflammation-mediated complications called inflammaging in dermal fibroblasts." (PMID 28900534, 2017). "Through the MAPK signaling pathways, AP-1 controls the expression of MMPs, especially MMP-1, MMP-2, and MMP-9, in inflammation-induced skin aging." (PMID 28900534, 2017). "In addition, many studies have reported that suppressing MMP-1 and MMP-3 increases dermal thickness and improves clinical signs of skin aging." (PMID 41471076, 2025). "Therefore, ELISA results can prove that more than 50 μM concentration of abalone peptide can increase the secretion of type I procollagen in cells, reduce the secretion of MMP-1 and MMP-9, and prevent skin aging." (PMID 31762729, 2019). "Hence, RR increased the expression of type I procollagen and decreased that of MMP-1 in reconstructed human skin, with the effect of protecting against UVB-induced skin aging or wrinkle formation." (PMID 28900534, 2017). "For example, it has been found that these aging fibroblasts could synthesize and secrete large amounts of matrix metalloproteinases 1 and 3(MMP-1 and MMP-3) to degrade skin collagen matrix to accelerate the progression of skin aging." (PMID 27486852, 2016). "Interestingly, cigarette smoke and UVA additively induced MMP-1 expression, suggesting that several environmental chemicals and UVR may interact and accelerate skin aging." (PMID 39865280, 2025). "Hence, LNF could reduce the secretions of MMP1 and MMP9 upon UV exposure, and subsequently prevent photo-induced skin aging." (PMID 35215366, 2022). "In skin aging, IL-6 is a regulator correlated with the generation of wrinkles on the skin, whereas COX-2 is well known to mediate the synthesis of prostaglandin E2 (PGE2), a lipid-derived signaling molecule involved in the production of MMP-1 and the suppression of collagen biosynthesis in HDFs." (PMID 34679744, 2021).
emphysema (44 papers, 2005 to 2024). "This scenario is accompanied by degradation of the extracellular matrix by MMP-1 (matrix metalloproteinase-1), secreted by alveolar macrophages, causing tissue destruction and emphysema." (PMID 38903812, 2024). "MMP-1 overexpression in the lung has been reported to be associated with emphysema in humans; notably, this gene was also found herein to be the most upregulated in the comparison between SEA and MEA." (PMID 36611613, 2022). "Alveolar macrophages are a major source of MMPs, including MMP-1, -9 and -12, which have been implicated in emphysema formation." (PMID 27455234, 2016). "This is greatly accompanied by extracellular matrix degradation by MMP-1 (matrixmetalloproteinase-1) secreted by alveolar macrophages causing tissue destruction and emphysema." (PMID 26322981, 2015). "Our lab has shown that increased MMP-1 synthesis can predispose the cellular environment to tumor development and tumor aggressiveness, in addition to its central role in emphysema." (PMID 25664615, 2015). "Joos and colleagues showed that the expression of specific MMP-1 alleles was associated with faster decline in lung function in smokers developing emphysema." (PMID 25664615, 2015). "Matrix metalloproteinase-1 (MMP-1) has been implied as an (etio)pathogenic factor in human lung and airway diseases such as emphysema, chronic obstructive pulmonary disease, chronic asthma, tuberculosis, and bronchial carcinoma and has been reported to be regulated by DEPs." (PMID 19337515, 2009). "When adjusted for smoking status, the overall emphysema score (defined using the density mask cutoff of −855 Hounsfield units) showed a borderline association with staining of type II pneumocytes (p = 0.073), with higher emphysema being positively related to staining for MMP-1." (PMID 24792232, 2014). "In particular, upregulation of MMP-1 expression can be involved in the progression of emphysema by regulating the MyD88/IRAK1 signalling pathway." (PMID 35388750, 2023). "The same investigators also studied MMP-1 transgenic mice and found morphological and physiological evidence for emphysema in this model expressing the human MMP-1 gene." (PMID 32878618, 2020). "MMP-1, which degrades collagen, and MMP-12, which degrades elastin, have both been strongly implicated in the development of smoke-induced emphysema, at least in animal models." (PMID 30789935, 2019). "The activation of TLR4 is a critical upstream signalling event in the smoke-induced induction of the collagenase MMP-1 in emphysema development." (PMID 31182072, 2019). "Animal models suggest a role for MMP-1, -9 and -12 in emphysema development while human studies demonstrate increased expression of MMP-1, - 2, -3, -8, -9, -10 and -12 in the airways of COPD subjects." (PMID 27460105, 2016). "Increased AM and ELF MMP-1 and MMP-9 expression have been linked to emphysema in humans and in animal models." (PMID 27446965, 2016). "In another study, Shiomi used a heterozygous line from a transgenic mouse model that overexpressed human MMP-1 and observed development of emphysema at 12 months with a decrease in type III collagen and increased lung compliance." (PMID 26052708, 2015). "It has been shown that in patients with emphysema, there is elevated concentration of MMP-1 and MMP-9 in BAL and increased expression of these MMPs in macrophages." (PMID 26126526, 2015). "Early animal studies directly demonstrated that increased local expression of MMP-1 promotes emphysema and lung degradation in transgenic mice expressing the human MMP-1 gene within lung parenchymal cells." (PMID 25664615, 2015). "Further evidence from animal and human studies supports a role for collagenolytic enzymes and, in particular, MMP-1 in the pathogenesis of emphysema." (PMID 24792232, 2014). "The amount of MMP-1 staining in alveolar macrophages in subjects with grade 2 emphysema was significantly greater than that of those with grade 1 emphysema (p = 0.03)." (PMID 24792232, 2014).